ERBB2 (erb-b2 receptor tyrosine kinase 2)
Diseases named in the same sentence as ERBB2 in open-access papers (continued):
Sharing a sentence is not in itself a finding about the gene and the disease.
tumor (continued). "Discovered here was the Erbb2-likeEx murine class, which associated with human HER2-enriched tumors even without highly expressing the Erbb2 gene; no mouse model from our previous studies mimicked this aggressive human tumor subtype." (PMID 24220145, 2013). "To evaluate whether Erbb2 altered the expression of these genes prior to tumor formation, we compared their expression in normal mammary glands from MMTV-NeuNT expressing mice and nontransgenic mice with the same mixed genetic background (minus MMTV-NeuNT)." (PMID 23593223, 2013). "Nonetheless, the remaining tumor cells expressed similar levels of erbB2 and erbB3." (PMID 24168763, 2013). "Furthermore, our preclinical data utilizing an inducible mouse model of mutant ERBB2 (A775_G776insYVMA) in lung epithelium revealed that the combination of afatinib and an mTOR inhibitor (rapamycin) were effective in mediating tumor shrinkage." (PMID 23630663, 2013). "A recent immunohistochemistry study of ErbB2 in neuroblastic tumours supports this conclusion." (PMID 23835063, 2013). "Overexpression of ErbB2 in the mammary glands of transgenic mice leads to tumor development." (PMID 23408142, 2013). "In addition, we found high expression of MBP-1 and HDAC1 in normal tissues and a statistically significant inverse correlation with ErbB2 expression in the paired tumor samples." (PMID 23421821, 2013). "Interestingly, increased expression of PGC-1α reduced the proliferation of ERBB2+ cells in vitro, but promoted tumor growth in vivo by promoting nutrient supply." (PMID 24304688, 2013). "Furthermore, the γ-secretase inhibitor, MRK003, was recently shown to inhibit tumor initiation in mice using an ErbB2 model of mammary tumorigenesis and mice treated with MRK003 had durable long-term relapse free survival." (PMID 23593654, 2013). "To assess whether loss of LKB1 affects the migration and invasion properties of ErbB2-dependent tumor cells, we analyzed the behavior of NIC-FF and NIC-LKB1 KD cells in vitro using the xCELLigence platform." (PMID 24280377, 2013). "The first report, where tumor development was driven by the ErbB2 oncogene, showed both faster onset of tumor genesis, higher primary tumor numbers, larger volume of primary tumors, as well as a higher number of metastases and larger volume of metastases in lipocalin-2 expressing mice." (PMID 22737251, 2012). "In addition, PI3K/Akt/mTOR signaling has been demonstrated to mediate the proliferation of embryonal tumor cells and to contribute to signaling by ErbB-2 and IGF-1R." (PMID 23056595, 2012). "Loss of FAK overexpression in tumours bearing both conditional FAK alleles did not affect ErbB2-induced Pyk2 overexpression." (PMID 22373082, 2012). "Moreover, expression of the ErbB-2 and ErbB-4 RTKs in embryonal tumor samples was shown to correlate with reduced patient survival, while Trk receptor expression correlated with a less aggressive tumor phenotype." (PMID 23056595, 2012). "It was recently suggested that amplification of ERBB2 comprises another resistance mechanism, and that acquired resistance is conferred by mutation of EGFR itself or results from expansion of tumor subclones with mutated or amplified KRAS." (PMID 23226389, 2012). "As expected, a dramatic reduction of ErbB2 expression in ErbB2-KD tumours was observed by IHC." (PMID 22393391, 2012). "Tumors appeared even later in the ErbB2 mouse (100% tumor free day 160)." (PMID 22737251, 2012). "Indeed, trastuzumab, which is an immunoglobulin G1 (IgG1), has been demonstrated to elicit ADCC against ErbB2+ tumour cells." (PMID 23202898, 2012). "Thus, it seems that the largest effect of lipocalin-2 on tumor development and aggressiveness is observed in the mouse model with the slowest onset of tumor genesis, the ErbB2 mouse." (PMID 22737251, 2012). "Finally, we tested if such compensatory mechanisms were also present in tumor cells isolated from a well described transgenic mouse model of ErbB2 mammary tumorigenesis." (PMID 23028720, 2012).
tumor (continued). "Indeed, we found that ERBB2-overexpressing cell lines are sensitive to TMI-1 as was a cell line derived from MMTV-ErbB2/neu tumor overexpressing activated ErbB2/neu (TgNeu27)." (PMID 23028451, 2012). "However, tumours from both these models are poorly metastatic suggesting that engagement of Pyk2/FAK/p130Cas signalling likely plays a more important role in the metastatic phase of ErbB2 tumour induction." (PMID 22373082, 2012). "HGF retained the ability to recover ErbB2 tumor cells treated with Iressa and Tarceva." (PMID 23028720, 2012). "However, several studies have established that the ErbB2/ErbB3 heterodimer functions as an oncogenic unit in ErbB2 amplified tumour cells." (PMID 23202898, 2012). "Our own work here with patient serum exosomes implies that GPNMB and/or ERBB2 may be tumor-specific exosome markers." (PMID 22848702, 2012). "Thus ErbB2-driven tumor cells possibly use a mechanism of recovery comparable to that found in non malignant NMuMG and MCF-10A cells (ErbB2)." (PMID 23028720, 2012). "Therefore ErbB2 tumor cells obtained from this transgenic model are dependent on activated EGFR for growth and survival and can be rescued by Met activation." (PMID 23028720, 2012). "Therefore we found that in this transgenic model, ErbB2 activation that drives tumor growth is coupled to EGFR kinase activity, which is fundamental for cell viability." (PMID 23028720, 2012). "Only two samples, both without other detected mutations, showed amplified ERBB2 (by virtue of higher than 5-fold tumor ERBB2 level relative to the level in the patient’s corresponding normal DNA)." (PMID 23226389, 2012). "Elevated ErbB4 ectodomain concentration also did not associate with ER or ErbB2 expression, tumor grade or postsurgical stage." (PMID 22761786, 2012). "Given that the ErbB2 tumour epithelia were completely devoid of FAK protein, we next evaluated whether these FAK-deficient tumours were capable of forming metastatic lesions within the lung." (PMID 22373082, 2012). "Interestingly, MUC4 expression was strongly repressed in ErbB2-KD tumours confirming the strong decrease in MUC4 level in ErbB2-KD cells observed by immunoblotting." (PMID 22393391, 2012). "Some studies have seen erbB2 over-expression in 20% to 60% of ECs, with this wide range indicating that the differences might depend on tumor stage or histology, or on the interpretation of the immunohistochemistry results." (PMID 21481261, 2011). "STAT1 also has a tumor suppressive role in mammary epithelium in ERBB2/neu-induced breast cancer." (PMID 22295238, 2011). "In addition, its expression on the cell surface of tumor cells makes ErbB2 a target for both antibodies and cell-mediated immunity." (PMID 24212954, 2011). "In the primary tumor, we found that both ERBB2 and KRAS were heterogeneously amplified." (PMID 22014070, 2011). "If present, anti-ErbB2 staining in tumor samples is a membrane staining, diffuse in the urothelium." (PMID 21483670, 2011). "In further analyses according to the tumor grading, the EC patients with a tumor grading G2 can be further stratified according to erbB2 CN ≤2 and erbB2 CN >2, which were again significantly negatively correlated to the survival rates of these EC patients (P = 0.03)." (PMID 21481261, 2011). "This may identify the presence of an NRG1–ERBB3/ERBB2 autocrine loop in these cases as in other tumour cell types, and could indicate that very low levels of receptor expression may be sufficient for signalling." (PMID 21364580, 2011). "Additionally, novel ERBB2-driven genes and transcript variants were revealed in these cell lines and were also validated in tumor specimens with high ERBB2 expression." (PMID 21731642, 2011). "Interestingly, increased ErbB-2 expression in tumour-initiating cells was shown to be Notch-1 dependent." (PMID 21847123, 2011). "Moreover, this novel immunoRNase is endowed with an effective and selective antiproliferative action for ErbB2-positive tumour cells both in vitro and in vivo." (PMID 21559015, 2011).
tumor (continued). "We enquired whether estimation of ER, PR and ERBB2 status of profiled tumor samples could be improved by using multiple probe sets representing these three genes and others with related expression." (PMID 22022496, 2011). "On the basis of these data and the known function of YB-1 in the regulation of erbB1 and erbB2 expression, it can be assumed that exposure of tumor cells to IR as it occurs during conventional radiotherapy may lead to an enhanced expression of erbB1 and erbB2." (PMID 21392397, 2011). "Taken together these data suggest that metastatic tumor cells express elevated levels of ErbB2." (PMID 20825649, 2010). "GRB7 may facilitate ERBB2-mediated signal transduction and tumor formation and has been suggested as a therapeutic target." (PMID 20932292, 2010). "Here it was observed that ErbB2 overexpression impaired tumor regression following IGF-IR downregulation thus suggesting that ErbB2 could potentially facilitate resistance to IGF-IR-directed therapies." (PMID 20825649, 2010). "Only one tumor, probably outlayer, showed high ErbB2 positivity." (PMID 20174572, 2010). "Furthermore, Erb-hcAb reduced the expressions of ErbB2 and vascular endothelial growth factor in treated cells as compared with untreated tumours." (PMID 20051960, 2010). "We then explored possible mechanisms through which ErbB2 augmented tumor growth." (PMID 20825649, 2010). "It was found that ErbB2 activates STAT3, and this activation may contribute to ErbB2-induced transformation and tumor progression." (PMID 27713313, 2010). "This pattern which suggests that hTid may exert oncosuppressive activity which breaks down during tumor progression is consistent with the role postulated for the L and I forms by in vitro studies employing the ErbB-2 over expressing cell lines." (PMID 20565727, 2010). "Only one tumor (case 96) had an amplicon on chromosome 17 that included the ERBB2 gene." (PMID 20712882, 2010). "In this study, it was determined that a modest increase in ErbB2 expression could accelerate primary tumor growth by enhancing proliferation immediately after cell colonization of the mammary gland." (PMID 20825649, 2010). "However, the level of ADCC induced against these tumours was significantly lower than that detectable against USPC showing amplification of the erbB2 gene by FISH." (PMID 19920829, 2010). "Studies have suggested that the dysregulation of cellular protein kinase C and protein kinase A activity could phosphorylate ErbB2 on Thr-686 for the activation and proliferation of tumor cells." (PMID 19878607, 2009). "Studies have verified that the HER-2/neu (c-erbB-2) oncogene (located on chromosome 17) is amplified and overexpressed in many tumor types, and have compared these results with immunohistochemical expression and clinicopathological data using Tissue Microarray or conventional slides." (PMID 19128465, 2009). "The partial degradation of ERBB2 in overexpressing tumours is worthy of note." (PMID 19183447, 2009). "A detailed inspection showed that one branch consisted of tumours belonging to the normal-like and ERBB2 subtypes and nearly half of the tumours of luminal A-type (group A), whereas the two other groups contained tumours predominantly belonging to the luminal A- or B subtype (groups B and C)." (PMID 19904269, 2009). "Tumours were classified into three main subtypes based on ER and ERBB2+ status." (PMID 22275966, 2008). "Besides improvements in the therapy it led to the concept that only a subgroup of tumours is ‘ERBB2 dependent’." (PMID 18454161, 2008). "Despite the fact that ALM was retained in the ErbB2‘+’/ErbB3‘−’ MVM2 tumours at statistically greater levels than seen in blood (0.98±0.09 vs 0.28±0.04 %ID/g; P<0.001), the levels of targeting were significantly lower than those seen in either the BT-474 or SK-OV-3 xenograft models (P<0.001)." (PMID 18841159, 2008).
tumor (continued). "Despite its correlation with proliferation genes, loss of PR expression, ERBB2 over-expression, and higher tumor grade, the Ox-E/ER index as a continuous variable did not achieve (although it exhibited a trend toward) significance with respect to DSS." (PMID 18631401, 2008). "A third cluster of tumours was identified with high expression of the ERBB2 cluster of probesets." (PMID 18803878, 2008). "Compared with normal L2 tissue, there was a four-fold increase in the amount of lactate in the MMTV-c-ErbB2 tumours and a six-fold increase in the bitransgenic tumours (p < 0.00001 between L2 and both tumours and p < 0.02 between ErbB2 and bitransgenic tumours, all n = 5)." (PMID 18700973, 2008). "Downregulation of ERBB2 by ATc led to a strong decrease in proliferating tumour cells." (PMID 18454161, 2008). "Radioiodinated ALM (125I-ALM) accumulated to similar levels (P=0.59) in two different ErbB2‘+’/ErbB3‘+’ tumour xenografts; 125I-ALM accumulated in BT-474 and SK-OV-3 tumour xenografts at 2.89±0.2 and 3.07±0.27% injected dose per gram of tissue (% ID per g), respectively, by 24 h post-injection." (PMID 18841159, 2008). "However, ErbB2‘+’/ErbB3‘+’ normal cells are predicted to be in vast excess compared with tumour cells in vivo." (PMID 18841159, 2008). "ATc induced downregulation of ERBB2 mRNA and protein led to a rapid reduction in tumour volume." (PMID 18454161, 2008). "Consistent with the proposed hypothesis that bivalent binding will increase tumour retention, optimal targeting of ALM in vivo requires expression of both ErbB2 and ErbB3 on the tumour cell surface." (PMID 18841159, 2008). "We used a mouse tumour model where growth of the primary tumours is 100% ERBB2 dependent." (PMID 18454161, 2008). "This may be explained by the fact that despite overexpression of ERBB2, tumour growth may predominantly depend on other oncogenes." (PMID 18454161, 2008). "The reciprocal positive regulation of Src by ErbB2 and ErbB2 by Src is strongly diminished in the bitransgenic tumours (in addition to the reduced activation of ErbB3) indicating a general decline in plasma membrane tyrosine kinase signalling in the bitransgenic tumours." (PMID 18700973, 2008). "We used a mouse tumour model that allows tetracycline-controlled expression of ERBB2." (PMID 18454161, 2008). "Therefore, the ideal tumour for trastuzumab therapy should not only overexpress but also be ‘ERBB2 dependent’." (PMID 18454161, 2008). "To test the hypothesis that bispecific targeting will increase tumour-targeting selectivity of antibody-based agents, we took advantage of two previously identified scFv, the anti-ErbB2 ML3.9 scFv and the anti-ErbB3 A5 scFv." (PMID 18841159, 2008). "The results show that the tumour cells in our mouse model are highly ERBB2 dependent." (PMID 18454161, 2008). "Tumours from bitransgenic mice overexpress the myr-Akt1 and ErbB2 transgenes, but there was dramatically less overexpression and phosphorylation of ErbB3, diminished phosphorylation of ErbB2, decreased level of EGFR protein and undetectable ErbB4 protein." (PMID 18700973, 2008). "This increase in tumour glycolytic activity was accompanied by significantly decreased intratumuor concentrations of glucose: 1.10 nmol/mg in the L2 mammary gland, 0.46 nmol/mg in ErbB2 tumours (p < 0.01) and 0.14 nmol/mg in bitransgenic tumours (p < 0.0004)." (PMID 18700973, 2008). "Untreated tumours expressed relatively high levels of ERBB2 mRNA and protein." (PMID 18454161, 2008). "Clearly, subgroups 9 (ERBB2 subtype) and 10 (basal subtype) were the more robust since most of the external tumours, which had been previously classified as ERBB2 and basal subtypes using the 500-gene intrinsic subset, were now assigned to subgroups 9 and 10, respectively." (PMID 17338809, 2007). "Indeed, 90% of the external basal-type tumours were classified into the subgroup 10 and 75% of the ERBB2 tumours were assigned to the subgroup 9." (PMID 17338809, 2007).
tumor (continued). "Moreover, while ER+ disease can be treated with hormone therapy, the only targeted therapy available for ER- patients is a monoclonal antibody that binds to the ERBB2 receptor and that is effective only for those ER- tumours with HER2/ERBB2 over-expression." (PMID 17683518, 2007). "However, these associations have only been marginally underscored using a multivariate regression model, except for the association between tumour phenotype and EGFR and/or ErbB2 overexpression." (PMID 17700572, 2007). "For example, anti-ErbB2 antibodies have been used to target doxorubicin containing liposomes or Pseudomonas exotoxin (immunotoxin) into the interior of ErbB2 overexpressing tumor cells." (PMID 17014727, 2006). "More recently, it was shown that aromatase inhibitors might provide more benefit than tamoxifen in patients with tumours positive for erbB-1 and/or erbB-2." (PMID 15743506, 2005). "To investigate whether immunisation with liposomal vaccine constructs can induce antitumour immunity and protect animals from subsequent tumour challenge, we used a model that allows evaluation of ErbB2-specific reagents in immunocompetent mice." (PMID 15812545, 2005). "A large majority (20 of 22 tumours) of BRCA1-associated tumours were also ER-negative and erbB2-negative in our study, in accordance with the high frequency of ER-negative tumours among BRCA1 carriers." (PMID 15642173, 2005). "Of these four tumours, three showed significant overexpression of ERBB2 mRNA." (PMID 16168117, 2005). "The frequency of erbB2 expression was similar in all three groups of familial tumours." (PMID 15642173, 2005). "The majority of tumor-derived cell lines expressed moderate to high levels of both erbB3 and erbB2." (PMID 16168116, 2005). "Since both erbB2 and erbB3 were highly expressed by our mammary tumor cell lines and HRG-promoted tumor cell proliferation, we sought physical evidence that the wt-rat-neu/ErbB2 could form a complex with the endogenous mouse erbB3." (PMID 16168116, 2005). "A question related to this matter is whether tumours with weak ERBB2 expression would respond to anti-ERBB2 therapy." (PMID 15545967, 2004). "Indeed, neutralising antibodies directed towards the EGF receptor or ErbB2 are either in clinical trials or have received FDA approval for the treatment of some tumours." (PMID 14735165, 2004). "Intraperitoneal injection of bystander cells secreting the fusion proteins did not lead to tumor regression suggesting that high local concentrations at the tumor site are necessary to target ErbB2 on tumor cells and to overcome elimination of BIg5 or Ig5 by neutralizing antibodies." (PMID 15242515, 2004). "Elucidating the biological effects of EGFR/erbB2 targeted therapeutics will enable patient tumor profiling to identify likely responders and the determination of biologically effective doses that allows chronic administration of these agents in order to maximise efficacy." (PMID 15305194, 2004). "Targeting of ErbB2 on tumor cells with antibody fusion proteins that interact specifically with the host immune system could be an efficient and specific approach for therapy of solid ErbB2+ tumors." (PMID 15242515, 2004). "Moreover, to evaluate if consecutive aphereses derived from the same patient display the same level of tumour contamination, we performed analysis of expression of ErbB2." (PMID 12569382, 2003).